ENSG00000277492
Gene: Small nucleolar RNA gene on chromosome X (70,846,079 to 70,846,295, reverse strand). Ensembl gene ENSG00000277492.
Gene Ontology:
Biological process: RNA processing
Cellular component: nucleolus
Homologues: Orthologues: mouse Gm24826 (79% identical), mouse Gm25203 (79% identical), mouse Snord3b-ps1 (79% identical). Paralogues in human: SNORD3D (82% identical).